SPIB (Spi-B transcription factor)
Description:
Sequence specific transcriptional activator which binds to the PU-box, a purine-rich DNA sequence (5'-GAGGAA-3') that can act as a lymphoid-specific enhancer. Promotes development of plasmacytoid dendritic cells (pDCs), also known as type 2 DC precursors (pre-DC2) or natural interferon (IFN)-producing cells. These cells have the capacity to produce large amounts of interferon and block viral replication. May be required for B-cell receptor (BCR) signaling, which is necessary for normal B-cell development and antigenic stimulation.
Synonyms: SPI-B
Tractability: No criterion of Open Targets' tractability assessment is met for any kind of drug.
Gene: Protein-coding gene on chromosome 19 (50,418,938 to 50,431,314, forward strand). Ensembl gene ENSG00000269404.
Subcellular location: Nucleus (Isoform 1); Cytoplasm (Isoform 2)
Gene Ontology:
Molecular function: DNA-binding transcription activator activity, RNA polymerase II-specific; protein binding; RNA polymerase II cis-regulatory region sequence-specific DNA binding; sequence-specific double-stranded DNA binding; DNA-binding transcription factor activity, RNA polymerase II-specific; DNA-binding transcription factor activity; sequence-specific DNA binding
Biological process: positive regulation of transcription by RNA polymerase II; cell differentiation; regulation of transcription by RNA polymerase II; immature B cell differentiation; regulation of DNA-templated transcription
Cellular component: cytoplasm; nucleus; chromatin
Genetic constraint (gnomAD): Loss-of-function variants: 6 observed, 20.79 expected, observed/expected ratio (o/e) 0.29, 90% interval 0.16 to 0.57. The upper end of that interval is the gene's LOEUF score, 0.57, which puts it in group 2 of 6, group 1 being the genes least tolerant of losing a copy. Missense variants: 302 observed, 285.57 expected, observed/expected ratio (o/e) 1.06, 90% interval 0.96 to 1.16. Synonymous variants: 166 observed, 137.26 expected, observed/expected ratio (o/e) 1.21, 90% interval 1.07 to 1.38.
Homologues: Orthologues: macaque SPIB (97% identical), pig SPIB (87% identical), dog SPIB (85% identical), mouse Spib (84% identical), guinea pig SPIB (84% identical), rat Spib (79% identical), rabbit SPIB (54% identical), tropical clawed frog spib (51% identical), zebrafish spi1a (40% identical). Paralogues in human: SPI1 (44% identical), SPIC (26% identical), ETV5 (23% identical), ETS1 (21% identical), ETV1 (21% identical), GABPA (21% identical), ETV6 (20% identical), ETS2 (19% identical), ETV4 (19% identical), FLI1 (19% identical), ERG (18% identical), SPDEF (18% identical), and 16 more.
Diseases named in the same sentence as SPIB in open-access papers:
SPIB is named in the same sentence as 60 diseases in open-access papers, as found by Europe PMC text mining. Sharing a sentence is not in itself a finding about the gene and the disease. The quoted sentences say what the papers report.
lung carcinoma (11 papers, 2018 to 2026). "For example, attachment-induced autophagy loss significantly increased anoikis resistance via Spi-B transcription factor activation in lung cancer cells." (PMID 35013120, 2022). "However, some studies have reported that SPIB plays a pro-tumor role, such as promotion of lung cancer invasion and possible association with poor prognosis in patients with liver cancer." (PMID 39153969, 2024). "CPBP is reported to be with lung cancer and SPIB is found to be associated with leukemia cells." (PMID 29653596, 2018). "SPIB is up-regulated in several malignancies, including lung cancer, B cell lymphoma, hepatocellular carcinoma, and ovarian cancer." (PMID 41583390, 2026). "It is well-established that SPIB is essential for the survival of mature B cells, playing a key role in diffuse large B-cell lymphoma, colorectal cancer, and lung cancer." (PMID 35969172, 2022). "For instance, SPIB reportedly exerts an inhibitory effect in colorectal cancer cells by activating NFkB and JNK signaling through MAP4K1 and promotes tumor-associated macrophage (TAM) recruitment by enhancing the expression of CCL4 in lung cancer." (PMID 35969172, 2022). "After stromal deprivation, the lymphocyte spectrum specific Ets transcription factor SPIB was activated and directly enhanced SNAP47 transcription in certain lung cancer cells." (PMID 38049825, 2023). "SPIB was previously reported to potentiate early mesenchymal invasion and epithelial cell metastasis by repressing CLDN2 nuclear transcription in lung cancer." (PMID 34094897, 2021). "Moreover, it has been shown that SPIB overexpression in mouse models increased infiltration of TAM, especially M2 macrophages, and promoted lung cancer progression." (PMID 35969172, 2022).
colorectal cancer (9 papers, 2014 to 2025). A primary or metastatic malignant neoplasm that affects the colon or rectum. "Over the years, many studies have linked SPIB to tumors, including lung, gastric, and colorectal cancers." (PMID 35969172, 2022). "Currently, no relevant studies have demonstrated a potential mechanism underlying the relationship between SPIB and the tumor genesis of colorectal cancer." (PMID 24959000, 2014). "SPIB is upregulated in various malignant tumors, including colorectal cancer, hepatocellular carcinoma, and gastric cancer." (PMID 38482016, 2024). "tsRNA-GlyGCC promotes colorectal cancer progression and 5-FU resistance through SPIB regulation." (PMID 40565315, 2025). "Additionally, tsRNA-GlyGCC promotes colorectal cancer progression and 5-FU resistance through SPIB regulation." (PMID 40565315, 2025). "Notably, SPIB, though few experimental studies described its detailed function and mechanism in colorectal cancer evolution, was identified as a common transcriptional hallmark shared by precancerous adenoma and tumor stages in our study." (PMID 34094897, 2021). "We also identified multiple down-regulated genes in colorectal cancer that are supported by recent studies on the gene products of the OTOP2, OTOP3, SPIB, and INSL5 genes." (PMID 37790614, 2023). "Therefore, SPIB may be related to not only carcinogenesis but also prognosis in colorectal cancer." (PMID 28229027, 2017).
lymphoma (9 papers, 2014 to 2026). A malignant (clonal) proliferation of B- lymphocytes or T- lymphocytes which involves the lymph nodes, bone marrow and/or extranodal sites. "ETS transcription factors, including SPIB and SPI1, are implicated in lymphoma pathogenesis and can be targeted by the small molecule TK216, which disrupts ETS-DHX9 interactions." (PMID 42130064, 2026). "The anti-tumor activity of TK216 is also observed in lymphoma, where it exerts its cytotoxic effects by disrupting the interaction between SpiB/Spi1 and RNA helicases, DDX5 and DHX9." (PMID 37895265, 2023). "Spriano and colleagues previously demonstrated that TK216 disrupted SPI1/SPIB interaction with RNA helicases in lymphoma models." (PMID 37895265, 2023). "Previously, Spriano and colleagues demonstrated that TK216 disrupts the interaction between Spi1/SpiB and RNA helicases in lymphoma." (PMID 37895265, 2023). "MCL is known to be dependent on constitutive activation of NF-κB, and as SPIB has been reported to regulate this pathway in other lymphomas we investigated the activity of the pathway in the different subclones." (PMID 29695239, 2018). "Functional annotation of SPIB 'A' genes suggests that they are significantly involved in pathways of importance for DLBCL lymphoma biology, such as the B cell receptor signaling pathway." (PMID 26099425, 2015). "In conclusion, the data presented here define the relationship of IRF4 to its endogenous partners in ABC-DLBCL cell lines identifying BATF as a principle IRF4 partner in addition to SPIB in these models of lymphoma." (PMID 24875472, 2014).
breast carcinoma (8 papers, 2013 to 2026). "Further analysis using the GEPIA database indicated that SPIB is highly expressed in breast cancer, which was further confirmed by the GSE42568 dataset." (PMID 41583390, 2026). "The study offers initial proof that SPIB directly binds to the UBD promoter to influence its transcription in breast cancer, promoting TNBC cell proliferation and migration by increasing UBD levels." (PMID 41583390, 2026). "Our analysis revealed that SPIB is predominantly localized in Mono/Macro and malignant cells of breast cancer, while UBD is primarily found in dendritic cells, Mono/Macro, and malignant breast cancer cells." (PMID 41583390, 2026). "Analogous to what is observed for ESR1 in breast carcinoma, SPIB 'A' genes show the highest gene expression in diffuse large B cell lymphoma, and the strongest response after silencing of SPIB by RNA interference in ABC DLBCL cell lines." (PMID 26099425, 2015). "This was done for two human TFs, ESR1 and SPIB in breast cancer and diffuse large B cell lymphoma, respectively." (PMID 26099425, 2015). "Analysing ESR1 and SPIB in breast carcinoma and activated B cell-like diffuse large B-cell lymphoma cell lines, respectively, revealed that the concerted binding to high and low affinity sites correlates best with gene expression." (PMID 26099425, 2015). "Furthermore, bioinformatic analyses have indicated that SPIB is involved in tumor immune infiltration and is regarded as a prognostic factor in breast cancer." (PMID 41583390, 2026). "Additionally, ULCAN database analysis showed that SPIB is abnormally overexpressed in breast cancer, particularly in TNBC tissues." (PMID 41583390, 2026). "In summary, we retrospectively identified five bone metastases‐related genes (KRT23, REEP1, SPIB, ALDH3B2, and GLDC) and constructed a gene expression signature‐based nomogram (GESBN) model for breast cancer patients by bioinformatics analysis." (PMID 30575323, 2019). "The roles of SPIB and STAT4 in breast cancer, while not fully elucidated, were both associated with improved immune cell activity and better overall survival in previous studies." (PMID 40723262, 2025). "The regulons SPIB, STAT4, and ZMYND8 were seen as the master regulators of immune modulation in PRLR-low patients who did not experience early breast cancer events." (PMID 40723262, 2025).
diffuse large B-cell lymphoma (8 papers, 2014 to 2025). "Not only that, SPIB had anti-apoptotic effect in diffuse large B-cell Lymphoma via PI3K–AKT pathway, which was associated with the poor prognosis and could be identified as a prognostic indicator in HCC." (PMID 36581948, 2022). "In diffuse large B-cell lymphoma, this includes inhibition of SPIB and SPI1 function, leading to transcriptional repression of oncogenic programs and induction of apoptosis." (PMID 41509392, 2025). "SPIB is a member of the E-twenty-six (ETS) transcription factor family involved in regulating B cell development and differentiation Moreover, previous studies have convinced SPIB as a novel prognostic biomarker in diffuse large B cell lymphoma that mediates apoptosis through the PI3K-AKT pathway." (PMID 36544484, 2022). "Notably, sets of genes upregulated after IRF4 and/or SPIB knockdown in activated B-cell (ABC)-type diffuse large B-cell lymphoma (DLBCL) cell line (IRF4_ABC_REPRESSED_ALL and IRF4_SPIB_ABC_REPRESSED_ALL; NES = 1.38 and 1.55; FDR q-value = 0.17 and 0.07) were also significantly enriched in NMZLs." (PMID 32585984, 2020).
leukemia (6 papers, 2015 to 2024). A malignant (clonal) hematologic disorder, involving hematopoietic stem cells and characterized by the presence of primitive or atypical myeloid or lymphoid cells in the bone marrow and the blood. "SPIB mRNA transcript levels are low in ETV6::RUNX1+ ALL relative to other leukemia subtypes, as the SPIB gene is directly activated by RUNX1 during B-cell development." (PMID 36766699, 2023). "This identified top 10 TFs involving in hematopoietic cells proliferation and differentiation (SPIB, ATF4) and pathogenesis of leukemia (CEBPB, CTCF)." (PMID 38693103, 2024).
B cell lymphoma (5 papers, 2015 to 2026). "Regarding this, it was reported that PU.1 and SpiB share some binding targets in B cell lymphoma, suggesting that they may work together as co-factors to regulate target genes in GC B cells." (PMID 37965309, 2023). "In addition to retrotransposon alterations, our integrated analysis of ATAC-seq and RNA-seq further reveals a potential link between GNAS KO plus HDAC3 inhibition and the ETS family transcription factors PU.1 and SpiB for transcriptional regulation of IFN signal activation in B-cell lymphoma." (PMID 39117798, 2024). "SPIB is amplified in Activated B Cell Diffuse Large B Cell Lymphomas (ABC-DLBCL) compared with other B cell lymphoma subtypes, and is translocated in the OCI-Ly3 ABC-DLBCL cell line leading to over-expression of SPIB mRNA compared with other lines." (PMID 25765478, 2015). "Similarly, exposure to TK-216, the clinical derivative of YK-4-279, reduced the interaction of ETS factors SPIB and SPI1 with these RNA helicases in B-cell lymphomas." (PMID 34221969, 2021).
colon cancer (5 papers, 2017 to 2024). "Upregulation of SPI1 or SPIB was found to be associated with poor prognosis in patients suffering from colon cancer." (PMID 34841706, 2021). "The HPA database demonstrated that the protein level of SPIB was lower in colon cancer tissues than in normal colonic epithelial tissues." (PMID 39153969, 2024). "Although SPIB promotion of cancer progression has been experimentally validated in colon cancer cells and ABC-DLBCL, more clinical or animal experiments are still needed to validate it." (PMID 35969172, 2022). "BiFC and co‐IP assays indicated that SIP‐11 treatment abolished the interaction between SPI1 and SPIB in colon cancer cells." (PMID 34841706, 2021). "Western blotting as well as real‐time qRT‐PCR measurement showed upregulation of SPI1 and SPIB protein in colon cancer specimens, while their transcript levels were reduced or elevated than those in normal counterparts, respectively." (PMID 34841706, 2021). "SPIB is overexpressed in several cancers including liver and colon cancers compared to the normal samples." (PMID 28752099, 2017). "Immunohistochemistry indicated that when compared with adjacent normal tissues, higher immunostaining of SPI1 was observed within cancerous cells and stroma of clinical colon cancer specimens, whereas elevated SPIB expression was mainly localized within cancerous tissues." (PMID 34841706, 2021). "In colon cancer cases, a positive correlation between SPIB and HK2 expression was noted (R = 0.1441, p < 1 × 10−4) or PGK1 (R = 0.3072, p < 1 × 10−4) and high levels of SPIB (p = 1.5 × 10−2) were linked with poor prognosis of colon cancer patients." (PMID 34841706, 2021). "There is a rich literature available suggesting that SPIB promotes trans-activation of SPI1 to increase glycolytic gene expression and drive the glycolytic process, proliferation, and invasiveness of colon cancer cells." (PMID 35969172, 2022). "In this study, based on evidence from co‐IP and BiFC assays, we found that ETS domains of SPIB and SPI1 were essential for their physical interaction in colon cancer cells." (PMID 34841706, 2021). "Importantly, SPIB facilitated transactivation of SPI1 to increase expression of glycolytic genes and drove glycolytic process, proliferation and invasiveness of colon cancer cells." (PMID 34841706, 2021). "The TCGA results indicated that SPIB, KRT24, PHLPP2, PLP1, BEST4, CA7, and C11orf86 were all downregulated, while KRT80, SLC39A10, AJUBA, FOXQ1, and CLDN1 exhibited upregulated levels in colon cancer." (PMID 32633726, 2020).
primary biliary cirrhosis (4 papers, 2016 to 2022). "Notably, the locus of human SPIB is associated with primary biliary cirrhosis, an autoimmune disease." (PMID 36277615, 2022).
acute lymphoblastic leukemia (3 papers, 2016 to 2022). Leukemia with an acute onset, characterized by the presence of lymphoblasts in the bone marrow and the peripheral blood. "Overexpression of SPIB inhibited cell proliferation and induces apoptosis in children with acute lymphocyte leukemia." (PMID 36581948, 2022).
adenoma (3 papers, 2010 to 2021). A neoplasm arising from the epithelium. "Immunohistochemistry validation showed that GTF2IRD1 enhanced significantly throughout the mucosa-adenoma-carcinoma sequence, while SPIB and NR3C2 kept decreasing in stroma during the disease course." (PMID 34094897, 2021). "In CRC, SPIB was demonstrated to correlate with CRC incidence risk and could act as a prognostic factor elsewhere In our case, SPIB expression increased in epithelium but decreased in mesenchyme in the sequence of normal mucosa-adenoma-tumor." (PMID 34094897, 2021). "For example, SPIB and NR3C2 were positively correlated with Module 1, indicating they are continuously inhibited during the mucosa-adenoma-carcinoma progression." (PMID 34094897, 2021). "SPIB is an adenoma condition-specific down regulated gene and its expression underwent a striking decrease in CRC tissues indicating that SPIB may serve as potential markers of CRC invasiveness and metastasis." (PMID 22496748, 2012).
autoimmune disease (2 papers, 2021 to 2022). A disorder resulting from loss of function or tissue destruction of an organ or multiple organs, arising from humoral or cellular immune responses of the individual to their own tissue constituents. "SPIB, as well as E2F2, GATA4 and TCF7L2 have been associated with other autoimmune diseases through differential gene expression and genetic polymorphisms, respectively." (PMID 33915751, 2021).
colitis (2 papers, 2012 to 2013). Inflammation of the colon. "Inactivation of T3SS-1 (through a mutation in invA) and T3SS-2 (through a mutation in spiB) renders S. Typhimurium unable to trigger gut inflammation in the mouse colitis model." (PMID 23637594, 2013).
colorectal adenoma (2 papers, 2013 to 2021). An adenoma that arises from the colon or rectum. "Notably, six DE-TFs, DACH1, GTF2IRD1, MEIS2, NR3C2, SOX9, and SPIB, were identified as having a dynamic signature along the colorectal adenoma-carcinoma sequence." (PMID 34094897, 2021). "Moreover, we found SPIB was significantly down-regulated in both colorectal adenoma and carcinoma, and was a hit of co-expression and prognosis analysis." (PMID 34094897, 2021).
melanoma (2 papers, 2023 to 2025). A malignant, usually aggressive tumor composed of atypical, neoplastic melanocytes. "In melanoma, several ETS TFs, including FLI1, SPI1, ELF4, ETV7, SPIB, and SPIC, are expressed at higher levels in Cluster A patients, whereas ETV5, ETV4, ELK1, ERF, and ETV2 showed increased expression in Cluster B patients." (PMID 41502516, 2025).
ovarian carcinoma (2 papers, 2024 to 2026). A malignant neoplasm originating from the surface ovarian epithelium. "For example, SPIB knockdown inhibits the immune escape of ovarian cancer cells and inactivates the JAK/STAT pathway." (PMID 39153969, 2024).
breast tumors (1 paper, 2011). "Indeed, scatter plots show that mRNA levels of IGFBP2 and SPIB, the two most differentially regulated genes, were significantly different between NIS-negative (0+) versus NIS-positive (3+) breast tumors." (PMID 21989294, 2011).
lymph node metastasis (1 paper, 2024). "In patients with lymph node metastasis of CRC, ETV4 expression was significantly upregulated, whereas SPDEF and SPIB expression was significantly downregulated." (PMID 38200280, 2024).
myeloma (1 paper, 2014). "SPIB alone or in conjunction with PU.1 made only a minor contribution to IRF4 occupancy in H929 myeloma cells." (PMID 24875472, 2014). "For comparison we additionally assessed the H929 myeloma cell line, which expresses high levels of PU.1 relative to SPIB." (PMID 24875472, 2014). "Equally, EICEs were recovered from sites occupied by IRF4 and SPIB or PU.1 and at sites occupied by IRF4 and PU.1 in the H929 myeloma." (PMID 24875472, 2014).